CRP (C-reactive protein)
Diseases named in the same sentence as CRP in open-access papers (continued):
Sharing a sentence is not in itself a finding about the gene and the disease.
Apnea (6 papers, 2012 to 2025). Lack of breathing with no movement of the respiratory muscles and no exchange of air in the lungs. "CRP has emerged as a useful clinical marker for OSA and cardiovascular comorbidities, due to its independent association with apnea severity and hypertension." (PMID 40437222, 2025). "Patients demographics, BMI, lipid profile or CRP were unaffected by omitting the treatment, yet all apnea severity measures were increased and neutrophil apoptosis was decreased as compared to the treatment night." (PMID 23088735, 2012). "For the two overlapping loci (CRP and HTR2A), associations with apnea phenotypes were again confirmed among CFS EAs and AAs, although the level of statistical significance did not meet the stricter threshold used in this paper due to the greater number of SNPs interrogated." (PMID 23155414, 2012).
autism spectrum disorder (6 papers, 2014 to 2026). A spectrum of developmental disorders that includes autism, and Asperger syndrome. "Maternal pregnancy levels of the inflammatory marker C-reactive protein (CRP) has been previously associated with autism spectrum disorder (ASD) in the offspring." (PMID 27093065, 2016). "This increase in C-reactive protein has been found to have a correlation with a risk for autism spectrum disorders." (PMID 27355027, 2014). "Keywords including "autism spectrum disorder," "oxytocin," "GABA," "Serotonin," "CRP," "IL-6," "Fe," "Zn," "Cu," and "gut microbiota" were used for the search." (PMID 38283894, 2024). "The higher CRP levels and higher plasma lipid levels in ASD compared with levels of healthy group observed in the present study suggest that the population of participants diagnosed with autism spectrum disorder may be exposed to subacute infections and/or inflammation." (PMID 32859040, 2020).
autoimmune hepatitis (6 papers, 2018 to 2026). Hepatitis caused by autoantibodies. "In this study, we also revealed that CRP levels are more effective than PCT in the diagnosis of bacterial infection in autoimmune liver disease-associated ACLF." (PMID 29623264, 2018). "Elevated CRP is an accurate marker for diagnosing bacterial infection in autoimmune liver disease-associated ACLF patients." (PMID 29623264, 2018). "CRP levels higher than 12.15 mg/L suggested bacterial infection in autoimmune liver disease-associated ACLF patients." (PMID 29623264, 2018). "Studies on CRP and autoimmune gastritis as well as autoimmune hepatitis are limited, but a study found elevated CRP in elderly onset autoimmune hepatitis, and a case report showed that it can be notably higher in possible relapse state." (PMID 37873776, 2023).
B-cell lymphoma (6 papers, 2018 to 2025). "One real world study of Axicabtagene Ciloleucel in patients with R/R B-cell non-Hodgkin lymphoma suggested that low CRP levels at baseline was associated with better response." (PMID 37153543, 2023). "The number of treatment lines before CAR-T therapy and C-reactive protein (CRP) >30 mg/l at the time of lymphodepletion has been reported to associate with poor progression-free survival (PFS) in R/R aggressive B-cell lymphoma, and CRP >30 mg/L further associated with shorter OS." (PMID 34395279, 2021). "Inflammatory markers such as interleukin-6 and C-reactive protein, and apoptotic biomarker, B-cell lymphoma-2 were also measured." (PMID 40893793, 2025). "Overall, the data indicate that cancer patients, especially those with B-cell lymphoma and certain solid tumors, have elevated TK1 and CRP levels compared to healthy controls, highlighting differences in inflammatory and tumor marker levels across these groups." (PMID 40351765, 2025).
babesiosis (6 papers, 2014 to 2021). Babesiosis refers to a condition caused by microscopic parasites that infect the red blood cells. "C-reactive protein, an acute phase protein, was higher in all groups of dogs with babesiosis compared to controls, indicating an active inflammatory state in babesiosis." (PMID 34603243, 2021). "CRP is a biomarker and indicator of inflammation, and plays a role of an acute phase reactant in babesiosis." (PMID 24885808, 2014). "Levels of CRP and haptoglobin were determined on day 0, day 1 and day 6 in serum of dogs with babesiosis and healthy dogs." (PMID 24885808, 2014). "In our study concentrations for CRP and SAA were significantly increased in the Babesia-infected group, indicating that IL-6 is associated with an inflammatory state in babesiosis, despite the fact that concentrations were not significantly different from the control dogs." (PMID 26953797, 2016). "C-reactive protein (CRP) and serum amyloid A (SAA) significantly increase in canine babesiosis but their levels are not related with the occurrence of complications neither with outcome." (PMID 29304171, 2018).
brain inflammation (6 papers, 2013 to 2024). "Additional laboratory tests, such as the C-reactive protein test, showed abnormally high results at 16.2 mg/l (above the normal limit of <5 mg/l), indicating tissue damage and brain inflammation." (PMID 38774558, 2024). "However, there has been little research on the influence of long-term chronic hypertension on the blood brain barrier and glial responses, so it is possible that CRP does not cross the BBB even if brain inflammation is present." (PMID 23978069, 2013).
chlamydia (6 papers, 2015 to 2023). "The POCTs most in demand were C-reactive protein ([CRP], 70%), chlamydia (69%) and N-terminal prohormone of brain natriuretic peptide ([proBNP], 68%)." (PMID 30564692, 2018).
choledocholithiasis (6 papers, 2023 to 2026). Presence or formation of gallstones in the common bile duct. "CRP ≥110.5 mg/L (B=2.35; 95% CI: 1.42-3.21; p<0.001), choledocholithiasis (B=15.31; 95% CI: 4.34-19.12; p=0.010), and MS (B=11.46; 95% CI: 5.00-21.49; p=0.017) were identified as significant predictors of prolonged LOS." (PMID 40786322, 2025). "In multivariate analysis, only CRP ≥110.5 mg/L (p<0.001), the presence of choledocholithiasis in 26 patients (17.3%; p=0.010), and Mirizzi syndrome in seven patients (4.7%; p=0.017) remained significant predictors." (PMID 40786322, 2025). "Patients with choledocholithiasis presenting with AGP may be diagnosed with AC if they have biliary dilatation and elevated CRP levels, which may cause uncertainty in ERCP timing for clinicians." (PMID 40474397, 2025). "Inflammatory markers such as C-reactive protein (CRP), white blood cell count (WBC), and total bilirubin (TBil), along with biliary complications like choledocholithiasis and Mirizzi syndrome, may have prognostic value." (PMID 40786322, 2025).
chronic hepatitis (6 papers, 2013 to 2024). An active inflammatory process affecting the liver for more than six months. "A previous study revealed that chronic hepatitis increases serum hs-CRP levels." (PMID 26177029, 2015).
Cushing syndrome (6 papers, 2019 to 2025). Cushing's syndrome (CS) encompasses a group of hormonal disorders caused by prolonged and high exposure levels to glucocorticoids that can be of either endogenous (adrenal cortex production) or exogenous (iatrogenic) origin. "Patients with active or treated Cushing syndrome exhibit elevated inflammatory markers, including C-reactive protein (CRP), interleukin-6 (IL-6), and tumor necrosis factor-alpha (TNF-α)." (PMID 40729034, 2025). "In a study conducted on Cushing’s syndrome (mean age = 48.6 ± 12.8 years), telomere length was inversely related to IL-6 and an inflammation marker C-reactive protein (CRP)." (PMID 38498288, 2024). "For example, an increase in serum haptoglobin (Hp) concentration in dogs with C-reactive protein (CRP) within reference intervals can indicate the increased production of endogenous glucocorticoids, as it occurs in hyperadrenocorticism." (PMID 37344860, 2023). "For example, an increase in Hp concentration in dogs with normal C-reactive protein (CRP) values can indicate the production of increased endogenous glucocorticoids, such as occurs in hyperadrenocorticism." (PMID 31189466, 2019).
disc degeneration (6 papers, 2011 to 2025). "These enriched pathways exhibited significant correlations with elevated serum inflammatory markers (CRP) and advanced disc degeneration, as determined by the Pfirrmann grading system." (PMID 41472810, 2025). "Compared to CRP, the model showcases superior efficacy in gauging both the extent of disc degeneration and the inflammatory activity in patients." (PMID 38007425, 2023). "A recent study demonstrated that a combination of age, C-reactive protein and CCL22 plasma levels could efficiently predict the recovery of patients who underwent spine surgery to treat disc degeneration." (PMID 39930483, 2025).
disseminated tuberculosis (6 papers, 2016 to 2025). "Factors including age, cough, nausea, headache, HGB, ALB, ESR and CRP have been proved to be significantly different between patients with miliary tuberculosis and miliary tuberculosis patients complicated with CNS tuberculosis." (PMID 28531173, 2017). "The median levels of ESR and CRP in miliary tuberculosis alone were significantly higher than those in patients complicated with CNS tuberculosis." (PMID 28531173, 2017). "In our study, elevated median levels of ADA, ESR and CRP were observed in patients with miliary tuberculosis alone, but only an elevated median level of ESR was observed in those complicated with CNS tuberculosis." (PMID 28531173, 2017). "In a sub-analysis of the patients with TS, median CRP level was higher when accompanied by pulmonary or miliary tuberculosis (4.2 vs. 1.8 mg/dL, p = 0.017)." (PMID 27733126, 2016). "He remained highly viremic for KSHV throughout the 2-year study period, during which he was infected with SARS-CoV-2 and developed disseminated tuberculosis, with steadily increasing levels of the inflammatory markers C-reactive protein (CRP), and interleukin-6 (IL-6)." (PMID 39998057, 2025). "Furthermore, univariate logistic regression analysis showed that cough, ESR, and CRP are protective predictors, whereas nausea, headache, ALB, and HGB are risk predictors for CNS tuberculosis in patients with miliary tuberculosis." (PMID 28531173, 2017). "Thus, elevated serum CRP may be a surrogate biomarker of a dysregulated detrimental immune response in disseminated tuberculosis." (PMID 40581751, 2025). "Many studies have shown decreased levels of HGB and ALB, elevated levels of adenosine deaminase (ADA) and CRP, and increased ESR in miliary tuberculosis patients." (PMID 28531173, 2017). "Our findings demonstrate that ALB is the key independent risk predictor and that other factors including cough, nausea, headache, HGB, ESR and CRP are non-independent predictors for CNS tuberculosis in patients with miliary tuberculosis." (PMID 28531173, 2017). "Thus, we concluded that ALB is the independent risk predictor, and other factors, including cough, nausea, headache, HGB, ESR and CRP are non-independent predictors for CNS tuberculosis in patients with miliary tuberculosis." (PMID 28531173, 2017).
dry eye (6 papers, 2012 to 2026). "Just prior to her dry eye referral, her previous hospital found C-reactive protein (CRP) and lactate dehydrogenase (LDH) levels to be significantly increased (CRP of 11.83 and LDH of 952), leading to a suspicion of an underlying malignancy." (PMID 29070018, 2017).
electrolyte disorders (6 papers, 2022 to 2025). "The results showed that 95.68% of the patients in COVID-19 Rehabilitation Clinic had symptoms, 70.10% had a dry cough, 12.36% had abnormal complete blood count or C-reactive protein, 19.35% had electrolyte disorder, and 2% had abnormal troponin or creatine kinase-MB." (PMID 37693834, 2023).
endophthalmitis (6 papers, 2017 to 2026). An infectious process affecting the internal structures of the eye. "We also presumed that it might have been other bacteria that we did not identify, and that could have been the cause of the orbital pain and subsequent spike in CRP levels, but we cannot ascertain this for sure because retroorbital pain can be caused by Nocardia endophthalmitis." (PMID 39597048, 2024). "Patients with ocular toxoplasmosis typically exhibited normal ESR and CRP (9/11, 82%) while patients with endogenous endophthalmitis had elevated ESR and/or CRP in 6/7, 86%." (PMID 30411142, 2019). "Patients with endogenous endophthalmitis exhibited CRP ≥ 10 mg/L in 5/7, 71%." (PMID 30411142, 2019). "In patients presenting with endophthalmitis and concurrent uncontrolled systemic infection, PCT showed a higher AUC than CRP (0.995 vs. 0.939)." (PMID 42122034, 2026). "In the HVIP1 vitreous, there were a number of significant correlations identified: CRP/Myoglobin, IGFBP-4/SAA, IGFBP-4/VCAM-1, and VCAM-1/SAA in the endophthalmitis group; MPO/NGAL, CRP/SAA, and Cystatin C/Myoglobin in controls; and NGAL/MMP-9 in both groups." (PMID 40563988, 2025). "The CRP level were significantly higher in the endogenous than exogenous endophthalmitis in the control group (p < 0.05) but not in the dialysis group (p = 0.065)." (PMID 28814278, 2017).
enteropathy (6 papers, 2013 to 2025). "Inflammation of the small intestine in children with enteropathy and systemic infection are accompanied by high levels of C-reactive protein (CRP) and release of inflammatory cytokines that impair production and action of chondrocyte growth factors." (PMID 40944251, 2025). "Intestinal biopsies collected in this study indicated that all children studied exhibited severe enteropathy with blunted villi (VH: 197.94 ± 65.58 μmm), severe enteric dysfunction (L/R ratio: 0.38 ± 0.36, LBP: 219.37 ± 107.71 μg/mL) and inflammation (CRP: 3950.15 ± 5931.50 ng/mL)." (PMID 29499047, 2018).
erectile dysfunction (6 papers, 2010 to 2025). Persistent or recurrent inability to achieve or to maintain an erection during sexual activity. "Men with erectile dysfunction presented higher cardiovascular risk, according to the CRP and FRS findings." (PMID 20963365, 2010). "Men with erectile dysfunction presented higher cardiovascular risk according to Framingham Risk Score and C-reactive protein measurements." (PMID 20963365, 2010). "This study explored the association between the C-reactive protein-albumin-lymphocyte (CALLY) index and erectile dysfunction (ED)." (PMID 40099259, 2025). "Men with erectile dysfunction presented higher cardiovascular risk according to the FRS criteria and CRP measurements." (PMID 20963365, 2010). "The CRP levels were significantly higher among men with erectile dysfunction (P = 0.04)." (PMID 20963365, 2010). "Men with erectile dysfunction were older, had higher BMI values, higher HOMA2-IR and higher triacylglycerols and hs-CRP but lower HDL-cholesterol levels." (PMID 34800144, 2022). "CRP and FRS did not correlate with the severity of erectile dysfunction." (PMID 20963365, 2010).
HELLP syndrome (6 papers, 2016 to 2025). A life-threatening condition that can potentially complicate pregnancy. "Regarding laboratory changes, discriminating count of white blood cells hemoglobin, platelet, hepatic enzymes, creatinine, ESR, CRP, LDH, and BUN were assessed, which mostly were in normal ranges, except one case with a high increase in ESR and LDH in a HELLP syndrome related case." (PMID 34001013, 2021).
herpes zoster (6 papers, 2017 to 2026). A common dermal and neurologic disorder caused by reactivation of the varicella-zoster virus that has remained dormant within dorsal root ganglia, often for decades, after the patient's initial exposure to the virus in the form of varicella (chickenpox). "A study investigating the diagnostic value of laboratory parameters (blood levels of CRP and leukocytes) revealed the potential of CRP to discriminate between bacterial SSTIs and herpes zoster supporting our findings." (PMID 38054000, 2023). "Research has indicated that certain inflammatory markers, such as C-reactive protein and albumin, can serve as early diagnostic indicators for predicting the onset of PHN, particularly in patients with acute herpes zoster." (PMID 41142151, 2025).
Hodgkins lymphoma (6 papers, 2013 to 2025). A heterogeneous group of malignant lymphoid neoplasms of B-cell origin characterized histologically by the presence of Hodgkin and Reed-Sternberg (HRS) cells in the vast majority of cases. "While remaining stable in controls, among patients with Hodgkin lymphoma the mean CRP levels increased throughout the year before diagnosis, mean ESR levels from 11 months pre-diagnosis, and mean platelet levels from around 7 months pre-diagnosis." (PMID 35817582, 2022). "Serum CRP levels also represent a valuable prognostic variable in Hodgkin lymphoma (HL) and aggressive NHL." (PMID 23724031, 2013).
hypoadiponectinemia (6 papers, 2014 to 2019). "Another study with 2044 participants showed that hypoadiponectinemia was significantly associated with incident MetS, even after adjusting for BMI, CRP, and HOMA-IR." (PMID 28670347, 2017). "Furthermore, hypoadiponectinemia is related to higher fasting plasma glucose and triglycerides, lower HDL cholesterol, and visceral obesity and also to higher levels of inflammatory cytokines (IL-6 and IL-1) and C reactive protein (CRP) in type 2 DM subjects." (PMID 28058263, 2016).
hypochromic anemia (6 papers, 2015 to 2025). Anemia caused by the reduction of hemoglobin in relation to the red cell volume. "In blood tests—hypochromic anaemia (Hb 114 g/l), C-reactive protein 8 mg/l, Ab to antigens (Ag) of cardiomyocyte nuclei—1:40 (N—abs); Ab to cardiac conductive fibres Ag—1:160 (N ≤ 1:40)." (PMID 39202422, 2024). "The initial workup of the patient revealed a neutrophilia, microcytic hypochromic anemia with a raised inflammatory marker C-reactive protein (CRP) of 147 mg/l (normal range 0.5–5 mg/l) with a normal stool and urinalysis." (PMID 35240480, 2022). "All full blood and biochemical tests were within normal limits except for mild hypochromic anemia (Htc = 38%), a moderate neutrophilic leucocytosis, and elevation of C-reactive protein (CRP = 18.9 mg/L)." (PMID 26681946, 2015).
ileus (6 papers, 2022 to 2025). Decrease in peristalsis in the absence of a mechanical bowel obstruction. "By supplementing with probiotics or synbiotics before and after the operation, it is possible to alleviate post-operative ileus by reducing the levels of pro-inflammatory molecules such as tumor necrosis factor-α, interleukin-6, C-reactive protein, and nitric oxide." (PMID 37373843, 2023). "Results of the two methods revealed abdominal pain, perianal fistula, ileus, elevated CRP, cobblestone appearance, involvement of jejunum were favor of UCD, while T-SPOT positive were favor of ITB, which indicated these three indexes were reliable for the identification of the the two disease." (PMID 35790774, 2022).